TNF (tumor necrosis factor)
Diseases named in the same sentence as TNF in open-access papers (continued):
Sharing a sentence is not in itself a finding about the gene and the disease.
tumor (continued). "Astaxanthin was associated with a higher quantity of tumor‐associated macrophages, infiltration of CD8+ T cells, Tumor Granzyme B, IL‐2, serum TNF‐α and interferon‐γ, genetic transcription of CXCL9, CXCL10, and CXCR3, and mRNA expression of cluster of differentiation." (PMID 40071130, 2025). "Furthermore, PTPR significantly enhanced T cell‐mediated cytotoxicity against tumor cells and upregulated the expression of TNF‐α and IFN‐γ in T cells." (PMID 40788220, 2025). "The detection of elevated TNFα in the margin revers to ongoing inflammation at the tumor border." (PMID 40431665, 2025). "Furthermore, polysaccharides reduce pro-inflammatory cytokines, including TNF-α and IL-6, which are critical contributors to the tumor-promoting microenvironment." (PMID 39852004, 2025). "These engineered CAR-Ms selectively engulfed NKG2DL-positive tumor cells through FcγRI-mediated phagocytosis while simultaneously secreting pro-inflammatory cytokines (e.g., TNF-α, IL-12), a dual functional output driven by coordinated activation of the PI3K-AKT and cGAS-STING signaling pathways." (PMID 41388305, 2025). "At low concentrations, TNF-α can activate immune cells and enhance the anti-tumor immune response." (PMID 40183013, 2025). "However, mice without TNF‐Rp55 show less mucosal damage, a reduction in macrophage and neutrophil infiltration, and reduced tumor formation, supporting the idea that TNF‐α plays a key role in the development and progression of CAC." (PMID 40548181, 2025). "Additionally, from diagnostic perspective, our ROC curve analysis indicated that TNF-α, IL-6 and IL-12 had the strongest ability to discriminate tumour tissue from the corresponding surgical margins (AUC 0.76, 0.65 and 0.65, respectively)." (PMID 41465261, 2025). "Furthermore, bigger tumor volumes were observed in VS patients with TNF-α high secretion capacity (TNF-α High versus TNF-α Low: 8.75 ± 9.19 cm3 versus 6.87 ± 11.44 cm3, p < 0.05)." (PMID 39923035, 2025). "NO also modulates tumor cell resistance to TNF-α-induced apoptosis." (PMID 41036604, 2025). "It is the resident TAMs of the CNS and secretes immunosuppressive factors like interleukin-10 (IL-10) and transforming growth factor-β (TGF-β) or other anti-tumor stimulating factors like IL-12 and tumor necrosis factor-α (TNF-α) based on the “heat” or “cold” status of the TME." (PMID 38720342, 2024). "Notably, this subset also expressed many genes associated with inflammatory CAFs (iCAF), a population of mesenchymal cells found in neoplastic tissues and predicted to respond to stimuli such as TNFα and IL-1β in the tumor microenvironment." (PMID 39485038, 2024). "Furthermore, the expression of inflammatory factors, namely NF-κB, TNF-α, and IL-6, in the tumor tissues was significantly attenuated." (PMID 38622523, 2024). "Interestingly, the levels of IFNγ and TNFα, which are critical inflammatory cytokines, were also remarkably increased in tumor-bearing mice." (PMID 38690266, 2024). "It is worth noting that the presence of high levels of TNF-α expressed in tumor cells may be related to the induction of an inflammatory response." (PMID 38255214, 2024). "M1 macrophages areclassically activated, and have strong antimicrobial and anti-tumor activities.They are stimulated by pro-inflammatory substances or inflammatory factors suchas tumor necrosis factor-α (TNF-α), lipopolysaccharide (LPS),and interferon γ (IFN-γ)." (PMID 39076555, 2024). "Moreover, inflammation can facilitate cancer metastasis by releasing specific cytokines such as IL-8 and TNF-α, which increase the invasiveness of tumor cells and prepare distant tissues for their arrival, thus promoting metastatic spread." (PMID 38474160, 2024). "Tumor immune evasion can arise through the loss of TNFα sensitivity, independent of perforin-mediated killing mechanisms." (PMID 38195677, 2024). "Moreover, PDTC decreased the TNF-α- and IL-1β-induced increase in the proliferation and migration abilities of tumor cells." (PMID 39726047, 2024).
tumor (continued). "M1 macrophages express Type I cytokines with an anti-tumor effect, such as tumor necrosis factor-α (TNF-α), interferon-γ (IFN-γ), IL-6; M2 macrophages express Type II cytokines, which inhibit T cell-mediated anti-tumor response, such as IL-10, IL-13, transforming growth factor-β (TGF-β)." (PMID 39735340, 2024). "Besides IL-12, the expression of cytokines such as TNF-α, IL1β and IL-6 is also critical for the activation of anti-tumour immune responses." (PMID 39487861, 2024). "It was observed that the group with TNFα overexpression had significantly larger tumor volumes." (PMID 38739004, 2024). "Furthermore, neoplastic cells secrete exosomes and factors such as TNF-α that alter adipocyte function, creating a feed-forward loop that fosters tumor progression." (PMID 39001498, 2024). "Notably, the upregulation of interferon and TNF signaling pathways suggests the presence of a “hot” tumor phenotype in some ESCC subtypes." (PMID 39234567, 2024). "It exhibits anti-inflammatory properties by reducing cytokines, such as IL-6 and TNF-α, which may inhibit tumor growth." (PMID 39766169, 2024). "Even though NK cells are best recognized for their cytolytic capacity, their ability to secrete cytokines such as IFNγ and TNFα may act as potential drivers of tumor progression." (PMID 38191418, 2024). "While tumor-specific mechanisms may counteract the immunosuppressive effects of TNFα inhibition during ICI therapy, a substantial systemic immunosuppressive effect persists, likely influencing cardiac immunity." (PMID 38473748, 2024). "In addition, overexpression of YAP1 induces the polarization of macrophages into the M2 phenotypes (tumor-associated macrophages) by regulating different genes such as iNOS, MerTK, IL-10, STAT3, CD163, CD206, Arg-1, CD86, and TNF-α in the naive macrophages." (PMID 39630608, 2024). "Blocking TNF-α or its receptor significantly diminishes cytotoxicity, while knocking down miR-125b-5p could increase the secretion of IFN-γ and TNF-α, thereby enhancing anti-tumor effects." (PMID 38840908, 2024). "Additionally, these effector CD8+ T cells are capable of releasing cytokines such as IFN-γ, TNF-α, and lymphotoxin-α (LT-α) which contribute to the killing and weakening of tumor cells." (PMID 39456702, 2024). "TNF-α and IL-10, which are secreted by M2-like macrophages, can induce PD-L1 expression in an autocrine manner, and inhibiting T cell function, which has a strong promoting effect on the occurrence and development of tumours." (PMID 38475858, 2024). "In addition, BETi increased the sensitivity of tumor cells to CD8+ T cells, and enhanced tumor growth inhibition in a TNF-dependent manner." (PMID 38347129, 2024). "In addition to studying the effects of TNF-α and IL-1β on tumor cells, we explored their effects on adjacent macrophages." (PMID 39726047, 2024). "Specifically, as compared to WT animals, A10-PPARα mice have more macrophages within the tumor and these intratumor (IT) macrophages expressed increased levels of cytokines such as tumor necrosis factor α (TNF-α), interleukin-6 (IL-6), IL-12/IL-23p40, and inducible nitric oxide synthase (iNOS)." (PMID 38746124, 2024). "In addition, in tumour tissues, the concentration of TNF-α was positively correlated with the number of TNFR2+CCR8+ Tregs." (PMID 37935468, 2024). "Notably, various functional pathways, such as the TNF signaling pathway, NF-kappa B signaling pathway, and ECM-receptor pathway, have been previously reported to be implicated in tumor progression and prognosis." (PMID 39044041, 2024). "Consequently, activated CD4+ TH cells release a range of cytokines, including IFN-γ, TNF-α, IL-1β, and IL-2, which collectively contribute to the anti-tumor effects." (PMID 39456702, 2024). "Also, NO and TNF-α have been identified as the major effector molecules involved in the destruction of tumor cells by activated macrophages." (PMID 39407494, 2024).
tumor (continued). "In summary, PDAC cells, particularly CSCs, upregulate PGLYRP1 in response to inflammatory signals, notably TNFα from both tumour and tumour microenvironment (TME) cells (eg, MΦ), as a strategy to mitigate its cytotoxic effects by blocking TNFα/TNFR1 signalling." (PMID 38754953, 2024). "CD8+ T cells have a key role in tumor eradication through their capacity to specifically recognize tumor antigens and to secrete potent effector molecules for tumor cell killing such as IFNγ, TNFα and granzymes." (PMID 38956389, 2024). "These pathways may also indirectly regulate IL-4, IL-9, and TNF-α, as these cytokines frequently interact with metabolic and proliferative pathways within the tumor microenvironment." (PMID 39727942, 2024). "Moreover, we examined the roles of several growth factors and inflammatory cytokines in PDL1 expression HNSCC cells, such as epidermal growth factor (EGF), LPS, IL-6, IL-1β, and TNF-α, commonly in tumor microenvironment." (PMID 38945975, 2024). "Gene expression for IL-1α, IL-1β, IL-6, IL-12, IL-23, CCL8, CXCL8, and TNF-α was significantly higher in the second-generation group, and a higher secretion of IL-6, IL-12, IL-23 and TNF-α was confirmed in the supernatant after 24 h of tumor cell co-cultivation in vitro." (PMID 39061247, 2024). "However, in the same study, both products were active in combination with targeted TNF therapy in mouse models and the F8-F8-SD-IL-15 was more efficient in reducing tumor metastasis formation in the lung thanks to the presence of the sushi domain." (PMID 39204319, 2024). "Its activation leads to increased secretion of pro-inflammatory cytokines such as IL-6, IL-1β, and TNF-α, which may promote inflammation and support a pro-tumor environment." (PMID 39273213, 2024). "Pro-inflammatory cytokines like TNF-α and IL-6 play key roles in promoting tumor progression." (PMID 39493763, 2024). "TNF-α upregulation has also been observed in ginsenoside Rh2-treated A549 tumour cells." (PMID 38361933, 2024). "Overall, the addition of MDMs to T cell-tumor cell co-cultures induced proinflammatory factors such as TNF secretion, elevated CTLA4 mRNA expression which is known to increase in response to T cell activation and simultaneously decreased anti-inflammatory CCR4 and TGFB1 mRNA expression." (PMID 39414902, 2024). "Also, MMP-9 expression in the tumor fibroblasts was found to be directly induced by tumor cell-derived TNF-α, EGF, or TGF-β." (PMID 39351229, 2024). "Furthermore, tumour cells in adipose tissue inhibit adipocyte differentiation by release of TNF-alpha and interleukin-11, thereby increasing the fibroblast:adipocyte ratio." (PMID 39251829, 2024). "Prospectively, combining TNF inhibitors with checkpoint blockade therapies may enhance the overall anti-tumor response by addressing both direct tumor signaling and the immune evasion mechanisms employed by tumors." (PMID 39682256, 2024). "TNF, originally identified as a pleiotropic cytokine, mediates innate immunity which is capable of inducing hemorrhagic necrosis of tumors; therefore, the history of this factor is tightly correlated with tumor immunotherapy." (PMID 38338920, 2024). "BCG activates two main inflammatory pathways: the TRIF/IRF3/IFNα/β pathway, which has a uniformly pro-immunogenic and anti-tumor role, and the NFκB/TNFα signaling pathway, which mobilizes immunogenic/anti-tumor but also immunosuppressive/tumor-promoting mediators in bladder cancer TME." (PMID 38667314, 2024). "While the PMA-Ionomycin-treated groups exhibited consistent outcomes across all experimental conditions, PD-1 KO enhanced the frequency of CAR-T cells concurrently releasing IFN-γ and TNF-α during co-culture with HER2+ tumor cells in the context of LA CAR-T cells." (PMID 38670972, 2024).
tumor (continued). "Since previous works suggest that PS exposure in non-apoptotic cells is possibly caused by oxidative stresses in the TME, we investigated the plausible contribution of oxidative stress-related factors, including tumor hypoxia and inflammatory cytokines such as tumor necrosis factor alpha (TNF-α)." (PMID 39272945, 2024). "Additionally, elevated TNF‐α levels were observed in patients with larger tumours (> 5 cm), greater lymph node metastasis, and higher TNM stage than in early‐stage patients." (PMID 39586790, 2024). "TAMs can exert a killing effect on tumor cells once activated by TNFα and interferon gamma (INF-γ)." (PMID 38483163, 2024). "In 1975, Carswell discovered a factor that could kill tumor cells, named tumor necrosis factor (TNF)." (PMID 39723039, 2024). "CD8+T cells release anti-tumor mediators such as TNF-α, and IFN-γ to destroy abnormal cells." (PMID 38590651, 2024). "We evaluated the cytokine profiles of cells isolated from CRC tumor tissue and observed a time-dependent increase in the expression of the pro-inflammatory cytokines TNFα and IFNγ for all different treatment groups, whereas downregulation of anti-inflammatory cytokine IL10." (PMID 39164686, 2024). "An inflammatory reaction is triggered by oxidative stress since TNF-α is a pro-inflammatory cytokine produced by macrophages that regulates the tumor cell necrosis, inflammation, and immune response and these macrophages are usually stimulated under oxidative stress." (PMID 38204250, 2024). "Tumor-associated exosomes are known to carry various proteins, RNAs, and factors such as vascular endothelial growth factor (VEGF), fibroblast growth factor (FGF), transforming growth factor β (TGF-β), and tumor necrosis factor (TNF)." (PMID 39334866, 2024). "Additionally, TNF-α and Granzyme B-producing populations were also increased in the tumor antigen-specific CD8+ T cells by HK-C60 administration." (PMID 38792006, 2024). "TNF-α is essential for the body’s defense mechanism and kills tumor cells." (PMID 39195177, 2024). "In addition, the combined treatment of Fn-OMV and oHSV significantly increased the release of nuclear high mobility group box 1 (HMGB1) and tumor necrosis factor-alpha (TNF-α) in tumor cells compared to oHSV treatment alone." (PMID 38693119, 2024). "Through the activation of CCR7, TNF modulates the increased motility of tumor cells." (PMID 38745115, 2024). "Moreover, HMGB1, in conjugation with TNF-α participates in the anti-tumor immune response of M1 macrophages in breast cancer." (PMID 37897664, 2024). "Furthermore, ailanthone induced the expression of the inflammatory factors TNF-α, IL-1β, and IL-6 in tumour tissues." (PMID 39723259, 2024). "In androgen-dependent tumours, TNFα signalling can drive the progression to castration-resistance." (PMID 39239510, 2024). "TNF-α also increases the expression of brain-derived neurotrophic factor (BDNF) and tropomyosin receptor kinase B (TrkB) in the development of SCZ and tumor, but the role of TNFR in mediating the association between the two diseases remains unclear." (PMID 38592583, 2024). "Additionally, there was a significant increase in the levels of IL-1β, IL-2, IL-6, IL-12β, IFN-γ, and TNF-α in the lavage fluid surrounding the cryoablated tumor." (PMID 38384806, 2024). "However, some neutrophils are thought to be tumor eliminating, and can create a prolymphocyte environment through production of TNFα and CXCL10, and antigen presentation." (PMID 38265267, 2024). "Preclinical studies suggest that TNF inhibition may provide a dual benefit of improved tumor control and reduced toxicity." (PMID 39403935, 2024). "The identification of HLA-II neoantigens enables HLA-II neoantigen vaccination and may benefit patients, as CD4+ T cells reactive to the HLA-II neoantigen (KVY15) identified by NESSIE produced IFN-γ and TNFα, suggesting their role in preventing tumor growth." (PMID 39292790, 2024).
tumor (continued). "Furthermore, the combination treatment significantly augmented the production of cytotoxic molecules, including Granzyme B, Perforin, and TNFα, in both primary and distant tumor‐infiltrating CD8+T cells." (PMID 38308189, 2024). "Similarly, TNFα has properties to stimulate proliferation, survival, migration, and angiogenesis in most cancer cells that are resistant to TNF-induced cytotoxicity, resulting in tumor promotion." (PMID 39451257, 2024). "Moreover, in the colon carcinoma cell line CT26 model, 40% of mice exhibited complete tumor regression associated with increased levels of pro-inflammatory cytokines IFN-γ, IL-6, and TNF-α in tumor and serum, and enhanced CD8+ T-cell infiltration." (PMID 39267734, 2024). "Since immune cells continuously recognize and eliminate tumor cells, this process may play a pivotal role in maintaining the sustained high levels of TNF-α, IFN-γ, MIP-1α, MIP-1β, and MIP-2 in the plasma." (PMID 38813211, 2024). "In addition, LAs reduce inflammatory cytokines (e.g., IL-6, TNF-α) and adhesion molecules, preserving NK cell function and promoting lymphocyte proliferation, which enhances anti-tumor immune responses." (PMID 39766169, 2024). "Furthermore, specific inflammatory cytokines, such as interferon (IFN) and tumor necrosis factor-alpha (TNF-α), are primarily orchestrated by DCs and tumor-associated macrophages (TAMs) in the TME, and significantly influence tumor progression and occurrence." (PMID 38185685, 2024). "For instance, proinflammatory cytokines such as interleukin-6 (IL-6) and tumor necrosis factor-alpha (TNF-α), released by T lymphocytes and activated macrophages, can stimulate cancer cells and stromal cells to produce other factors that enhance tumor survival, proliferation, and angiogenesis." (PMID 38539448, 2024). "TNF is a substance that can damage tumor cells and make them necrotic." (PMID 38994338, 2024). "Finally, in vivo experiments involving subcutaneous injection of GH3 cells into the scalp revealed that TNFα overexpression in GH3 cells leads to significantly increased tumor volume and more pronounced bone destruction." (PMID 38739004, 2024). "The relationship between RELT and cancer may be another example of a protein that can either promote apoptosis or pro-tumorigenic functions, similar to the ability of TNFα treatment to induce either apoptosis or promote tumor growth in TNBC." (PMID 39767574, 2024). "Macrophages can be activated to kill tumor cells by producing NO and TNF-α." (PMID 39407494, 2024). "This suggests that TNF-R1 is the more relevant receptor for the anti-tumor activity of TNF-α." (PMID 38339276, 2024). "Compared to TNF-α, IL-10 and IL-17 play a more direct role in the mechanism of tumor immune escape." (PMID 38734702, 2024). "Notably, TNF-α regulates many critical processes of tumour promotion and progression, with clinically elevated serum levels noted in individuals suffering from pre-neoplastic and malignant diseases." (PMID 38310564, 2024). "The hypothesis predicts that blockade of IL-6 and its companion cytokines, TNF-α, and IL-1β, will convert an immunologically “cold” (unresponsive) tumor to one that is “hot” (immune responsive)." (PMID 39512605, 2024). "recently showed that TNF-α promotes tumor lymph angiogenesis in HNSCC." (PMID 39411143, 2024). "TNF-α is produced by tumor cells, stromal fibroblasts, and inflammatory cells." (PMID 39273323, 2024). "This expression is induced by tumor-derived tumor necrosis factor (TNF)-α or inflammatory stimuli." (PMID 39201787, 2024). "Furthermore, cell–cell interaction analysis revealed their intricate interactions with tumor cells, macrophages, and T cells, and their contribution to TNF-induced apoptosis." (PMID 39767767, 2024).